ORC2 (origin recognition complex subunit 2)
Description:
Component of the origin recognition complex (ORC) that binds origins of replication. DNA-binding is ATP-dependent. The specific DNA sequences that define origins of replication have not been identified yet. ORC is required to assemble the pre-replication complex necessary to initiate DNA replication. Binds histone H3 and H4 trimethylation marks H3K9me3, H3K20me3 and H4K27me3. Stabilizes LRWD1, by protecting it from ubiquitin-mediated proteasomal degradation. Also stabilizes ORC3.
Synonyms: ORC2L
Tractability: Small molecule: a structure with a bound ligand is known. PROTAC: ubiquitination databases record sites on it; its protein half-life has been measured.
Gene: Protein-coding gene on chromosome 2 (200,908,973 to 200,963,702, reverse strand). Ensembl gene ENSG00000115942.
Subcellular location: Nucleus
Subcellular location (Human Protein Atlas): Nucleoplasm; Cytosol
Pathways (Reactome):
DNA Replication: Activation of the pre-replicative complex; Assembly of the ORC complex at the origin of replication; Assembly of the pre-replicative complex; CDC6 association with the ORC:origin complex; Orc1 removal from chromatin
Cell Cycle: Activation of ATR in response to replication stress; E2F-enabled inhibition of pre-replication complex formation
Gene Ontology:
Molecular function: protein binding; DNA replication origin binding
Biological process: DNA replication initiation; negative regulation of transcription by RNA polymerase II; DNA replication
Cellular component: centrosome; chromosome, telomeric region; heterochromatin; membrane; nuclear origin of replication recognition complex; nucleoplasm; nucleus; origin recognition complex; chromatin; inner kinetochore
Genetic constraint (gnomAD): Loss-of-function variants: 9 observed, 24.21 expected, observed/expected ratio (o/e) 0.37, 90% interval 0.22 to 0.65. The upper end of that interval is the gene's LOEUF score, 0.65, which puts it in group 2 of 6, group 1 being the genes least tolerant of losing a copy. Missense variants: 231 observed, 277.16 expected, observed/expected ratio (o/e) 0.83, 90% interval 0.75 to 0.93. Synonymous variants: 89 observed, 99.36 expected, observed/expected ratio (o/e) 0.9, 90% interval 0.75 to 1.07.
Homologues: Orthologues: chimpanzee ORC2 (99% identical), macaque ORC2 (98% identical), dog ORC2 (92% identical), rabbit ORC2 (91% identical), pig ORC2 (91% identical), guinea pig ORC2 (85% identical), mouse Orc2 (79% identical), rat Orc2 (79% identical), tropical clawed frog orc2 (59% identical), zebrafish orc2 (43% identical), Drosophila melanogaster Orc2 (37% identical), Caenorhabditis elegans orc-2 (18% identical).
Diseases named in the same sentence as ORC2 in open-access papers:
ORC2 is named in the same sentence as 22 diseases in open-access papers, as found by Europe PMC text mining. Sharing a sentence is not in itself a finding about the gene and the disease. The quoted sentences say what the papers report.
colon cancer (6 papers, 2016 to 2026). "First hypomorphic mutation made in the ORC2 gene in HCT116 colon cancer cells decreased ORC2 protein levels by 90% and cells were still viable and could proliferate." (PMID 40304571, 2025). "Knockouts of ORC1, ORC2, ORC5, or ORC2/ORC5 in human colon cancer cells yielded viable clones that were able to load MCM onto DNA and replicate their genomes." (PMID 41423967, 2026). "It was identified that HCT116 colon cancer cells initiate DNA replication normally in the absence of ORC5 and ORC2 proteins." (PMID 36362041, 2022).
pancreatic cancer (2 papers, 2022 to 2025). "In pancreatic cancer, Polo-like kinase 1 phosphorylation of ORC2 maintains DNA replication on gemcitabine treatment." (PMID 35711825, 2022). "Interestingly, a study in pancreatic cancer discovered that ORC2 phosphorylation by polo-like kinase 1 promotes DNA replication under stress conditions and contributes to gemcitabine resistance, suggesting its potential importance in cancer progression." (PMID 40316534, 2025).
prostate carcinoma (2 papers, 2013 to 2014). A carcinoma that arises from epithelial cells of the prostate gland. "There are other pre-RC components, such as Orc2, Cdt1, and Mcm7, that are also reported to be associated with AR in prostate cancer cells." (PMID 23437213, 2013).
breast carcinoma (1 paper, 2016). "For example, ORC2 siRNA decreased S-phase DNA content in MCF10A breast cancer cells." (PMID 27701460, 2016).
Chronic colitis (1 paper, 2014). A chronic inflammatory disease of the large intestine (colon, cecum and rectum). "Thus, the potential DEGs (Orc2 and Orc5) can be used as new and meaningful molecular markers in the evolution process of chronic colitis to colitis-associated CRC in this model." (PMID 24743346, 2014).
colorectal carcinoma (1 paper, 2021). A malignant epithelial neoplasm that arises from the colon or rectum and invades through the muscularis mucosa into the submucosa. "Subsequently, in human colorectal carcinoma cell line HCT116, ORC1, and ORC2 were reported to be non-essential for cell proliferation." (PMID 33522487, 2021).
glioma (1 paper, 2024). A benign or malignant brain and spinal cord tumor that arises from glial cells (astrocytes, oligodendrocytes, ependymal cells). "Subsequent analysis revealed a significant increase in the expression of ORC6 mRNA and protein in the oeORC6-expressing P1 glioma cells, where the expression of ORC2 mRNA and protein remained unaltered." (PMID 38971772, 2024). "The use of the same shORC6-s1 treatment along with puromycin selection led to a substantial reduction in ORC6 mRNA across these glioma cells, while the expression of ORC2 mRNA remained unaltered." (PMID 38971772, 2024).
HCMV infection (1 paper, 2012). "The effect of ORC2 depletion on HCMV infection was profound." (PMID 22586460, 2012). "Clearly, removal of the cellular factor ORC2 during HCMV infection did not impede viral DNA synthesis and actually led to an increase in viral replication." (PMID 22586460, 2012).
lung carcinoma (1 paper, 2023). "Susana Gonzalez and colleagues indicated that repression of the INK4/ARF locus could suppress the oncogenic activity of Cdc6 in lung cancer, which could inhibit the formation of multiprotein complexes, including ORC2, Cdc6, and MCMs." (PMID 36205357, 2023). "The lung cancer dataset showed that the DNA alteration percentages of the ORC complex were 1.9% (ORC1), 1.7% (ORC2), 1.5% (ORC3), 1.2% (ORC4), 2.2% (ORC5), and 1.4% (ORC6)." (PMID 36205357, 2023).
lymph node metastasis (1 paper, 2023). "ORC2 was correlated with lymph node metastasis in LUAD patients." (PMID 36205357, 2023).
mastitis (1 paper, 2022). Inflammation of breast tissue during lactation or postpartum due to an obstructed duct or infection. "In this study, the increased gene expression of ORC1, ORC2, ORC4, MCM3, MCM5, and MCM6 in the neutrophils of cows with high SCCs indicated that the cell cycle may be activated in neutrophils in high mastitis risk cows during the transition period." (PMID 35572521, 2022).
cancer (13 papers, 2015 to 2025). A tumor composed of atypical neoplastic, often pleomorphic cells that invade other tissues. "It should be noted, however, that sgRNA screens revealed that the ORC2 gene was essential for viability in the cancer cell lines mutated for ORC2, suggesting that vanishingly small amounts of the ORC2 gene product are required for some processes essential for cell proliferation." (PMID 38567819, 2024). "Additionally, ORC2 was associated with prevention of apoptosis induction and could serve as a potential target for cancer therapy by inhibition of cancer cell stemness." (PMID 36362041, 2022). "On the other hand, we have generated cancer cell lines in which one of the ORC subunits, ORC1, ORC2, or ORC5, is mutationally inactivated by CRISPR–Cas9, and the cells are still viable and proliferate with DNA replication." (PMID 40530691, 2025). "In the cancer cells, we had removed the initiator methionine of the Orc2 gene." (PMID 40304571, 2025). "Yet, it has been possible to select cancer cell lines that have mutations in Orc1, Orc2, or Orc5 and do not express detectable levels of the proteins and yet load MCM2-7 to the chromatin and replicate their DNA as they proliferate in culture." (PMID 40304571, 2025). "It is known that cancer cells can proliferate normally with 10% of the levels of ORC2." (PMID 33522487, 2021). "Our results indicated that the expression of ORC1, ORC2, ORC3, ORC4, ORC5, and ORC6 was different in the seven common types of tumor‐infiltrating immune cells, such as B cells, CD4 T cells, CD8 T cells, NK cells, macrophages, endothelial cells, and cancer‐associated fibroblasts." (PMID 36205357, 2023). "Cancer cell lines in culture can survive and replicate DNA replication after genetic inactivation of individual ORC subunits, ORC1, ORC2, or ORC5." (PMID 40304571, 2025). "Mapping of origins in cancer cell lines engineered to delete three of the subunits, ORC1, ORC2, or ORC5, shows that specific origins are still used and are mostly at the same sites in the genome as in wild-type cells." (PMID 40530691, 2025). "It is also worth noting that in cancer cells in culture, we are seeing a near normal level of loading of MCM2-7 on chromatin when Orc1, Orc2, or Orc5 genes are deleted, and that 60% of the origins of replication remain at the same sites as in WT cells." (PMID 40304571, 2025). "A few human cancer cell lines have been created by CRISPR-Cas9 mediated genome engineering where ORC1, ORC2, and ORC5 cannot be detected by regular immunoblots and yet the cell lines survive, proliferate and replicate DNA with the normal complement of origins of replication." (PMID 40304571, 2025). "Similar to the effect of the ubiquitination-resistant mutant of Geminin, expression of cancer-derived SPOP mutants also increased Cdt1 binding to MCM2, CDC6, and ORC2 but had no influence on Geminin binding to Cdt1." (PMID 34599168, 2021). "Even in humans, ORC1, ORC2, and ORC5, the essential components of the eukaryotic replication initiation complex, are not essential in some cancer cell lines, suggesting that mechanisms of replication initiation rescue may also operate beyond the bacterial kingdom." (PMID 40439200, 2025).
tumor (4 papers, 2020 to 2025). "The significant reduction in tumor growth, coupled with decreased expression of Ki-67, c-Myc, and ORC2 in tumor tissues, provides the evidence for the translational potential of this combination therapy." (PMID 40316534, 2025). "Immunohistochemical analysis of tumor tissues revealed that the combination treatment significantly decreased the expression of Ki-67 (proliferation marker), c-Myc, and ORC2 in both H23 and H2122SR xenografts." (PMID 40316534, 2025). "These in vivo results along with in vitro results validate our mechanistic findings and demonstrate that anlotinib combined with KRAS-G12Ci effectively overcomes resistance through modulation of the c-Myc/ORC2 axis, resulting in significant tumor suppression." (PMID 40316534, 2025). "Validation studies of the expression levels of ORCs in HCC were performed in the GEPIA database, which indicated that ORC1 and ORC3-6 presented high levels of expression in tumor tissues, while ORC2 showed the opposite results." (PMID 32194798, 2020). "Similarly, ORC2 knockdown reinstated the combination treatment’s inhibitory effects on tumor growth and viability in MYC-overexpressing cells." (PMID 40316534, 2025).
infection (3 papers, 2012 to 2025). The state of being infected such as from the introduction of a foreign agent such as serum, vaccine, antigenic substance or organism. "The dilution of the undeleted MEF lysate on the same blot suggests, that if any ORC2 protein is expressed in the MEF after adeno-Cre infection, it is <10% of that in the undeleted MEF." (PMID 40304571, 2025). "At low levels of E2 present in basal cells, ORC2 inhibits viral replication and thereby prevents a lytic infection." (PMID 27701460, 2016). "In this study, we have used siRNA knockdowns of Cdc6, Cdt1, ORC2 and MCM7 to address their role, if any, in HCMV DNA replication and show that infection of cells depleted for these proteins results in enhanced viral lytic DNA replication." (PMID 22586460, 2012). "Consistent with this, at 5 d after adeno-Cre infection, the ORC2 protein is not detected in the MEF population." (PMID 40304571, 2025).
ORC2 also shares sentences with these, for which no sentence is quoted: colitis (1 paper); DiGeorge syndrome (1); hepatocellular carcinoma (1); intrahepatic cholangiocarcinoma (1); leprosis (1); malaria (1); non-small cell lung carcinoma (1); vitiligo (1).